CD34 (CD34 molecule)
Diseases named in the same sentence as CD34 in open-access papers (continued):
Sharing a sentence is not in itself a finding about the gene and the disease.
spindle cell hemangioma (1 paper, 2022). Spindle cell hemangioma (SCH), also known as spindle cell hemangioendothelioma, is a rare benign vascular tumor either solitary or multiple, characterized by cavernous blood vessels separated by spindle cells reminiscent of those in KaposiBs sarcoma and located in the dermis and subcutis. "The presence of CD34 immunoreactivity in the spindle cells determines the diagnosis of spindle cell hemangioma." (PMID 36611301, 2022).
spindle cell rhabdomyosarcoma (1 paper, 2021). An uncommon variant of rhabdomyosarcoma characterized by the presence of whorls of spindle cells forming a storiform pattern. "Immunohistochemical analysis showed negative staining with Cytokeratin, S100, CD34, Stat6, h-Caldesmon and EMA while the tumour cells were positive for desmin, myogenin, smooth muscle actin, CD-99 and MyoD1 thus confirming the diagnosis of spindle cell rhabdomyosarcoma." (PMID 34104191, 2021).
squamous intraepithelial lesions (1 paper, 2020). "The appearance of α-SMA-positive myofibroblasts and the disappearance of CD34-positive stromal cells are linked with the conversion of squamous intraepithelial lesions (SILs) to SCC." (PMID 33383808, 2020). "Studies showcased that normal mucosal stroma and squamous intraepithelial lesions (SILs) enclosed CD34-positive cells that were scattered, but there was an absence of alpha smooth muscle actin (α-SMA)-positive myofibroblasts." (PMID 33383808, 2020).
ST Elevation Myocardial Infarction (1 paper, 2020). A myocardial infarction that produces elevation in the ST segments of the ECG. "The purpose of this study was to compare plasma concentrations of CD31+/CD42b− MPs, CD62E+ MPs, and CD34+ MPs across CAD, acute CV events (non‐ST elevation myocardial infarction (NSTEMI)), and healthy controls." (PMID 32748505, 2020).
systolic heart failure (1 paper, 2022). Heart failure caused by abnormal myocardial contraction during systole leading to defective cardiac emptying. "Autologous CD34+ cell transplantation is safe and effective in treating AMI, refractory angina, and systolic heart failure, according to numerous clinical studies." (PMID 36660500, 2022).
T cell deficiency (1 paper, 2023). "Overall this is in line with normal T cell differentiation of CD34+ cells from P3 in an ATO, suggesting that HSCT cannot robustly correct the T cell deficiency in this condition." (PMID 37689091, 2023).
T-cell immunodeficiency (1 paper, 2021). A broad classification of disorders that affect the cell-mediated aspect of the immune response. "Prolonged T-cell immunodeficiency observed after conventional T-cell graft depletion by CD34+ cell selection is a troublesome barrier to better clinical outcomes." (PMID 35242727, 2021). "However, the CD34+ selected process induces prolonged post-transplant T-cell immunodeficiency." (PMID 35242727, 2021).
TAFRO syndrome (1 paper, 2019). "To investigate the renal pathophysiology of TAFRO syndrome, we performed immunohistological staining of vascular endothelial growth factor (VEGF)-A, CD34, and D2–40, in our case and a normal control kidney." (PMID 31623576, 2019).
tendinopathy (1 paper, 2015). "Staining was prominent in endothelial cells (CD34+) and particularly fibroblast-like cells, namely tenocytes, which are considered pivotal to the regulation of early tendinopathy." (PMID 25857925, 2015).
tenosynovial giant cell tumor (1 paper, 2024). A tumor usually arising in the synovium of joints, bursa or tendon sheath. "Tenosynovial giant cell tumors have small histiocytic, large amphophilic, multinucleated giant and foam cells and are negative for S100 and CD34." (PMID 39202049, 2024).
thoracic neoplasms (1 paper, 2024). "In the setting of thoracic neoplasms, it has been described that SMARCA4 loss correlates with poorer outcome and expression of SOX2, CD34, and SALL4, and SMARCB1 loss is mainly seen in thoracic neoplasms of a mesenchymal lineage." (PMID 39125735, 2024).
Thromboembolism (1 paper, 2023). The formation of a blood clot inside a blood vessel that subsequently travels through the blood stream from the site where it formed to another location in the body, generally leading to vascular occlusion at the distant site. "Combined with the results of gene expression and gene enrichment, CD34+ mononuclear cells in PV deflected stronger adhesion effect than apoptosis, in accordance with the characteristics of PV prone to thromboembolism." (PMID 36873934, 2023). "Finally, our results suggested that CD34+ mononuclear cells in bone marrow or peripheral blood contributed significantly less to thromboembolism than other types of cells." (PMID 36873934, 2023).
thymoma (1 paper, 2016). A neoplasm arising from the epithelial cells of the thymus. "These thymomas were negative for the expression of Human Leukocyte Antigen (HLA), meaning they had no human component, presented high rates of proliferation and they were positive for the hematopoietic progenitor cell antigen CD34." (PMID 27355476, 2016).
thyroid (1 paper, 2018). "Immunohistochemistry was used to detect PSMA expression in 101 thyroid lesions, while neovasculature was identified by CD34 immunostaining." (PMID 29515776, 2018).
thyroid angiosarcomas (1 paper, 2024). "By immunohistochemistry, thyroid angiosarcomas are strongly and diffusely positive for pan-endothelial markers, i.e., CD31, CD34, FLI-1 and ERG, but lack expression of thyroid-related immunomarkers including thyroglobulin, TTF1 and PAX8." (PMID 39422760, 2024).
Thyroid-Associated Ophthalmopathy (1 paper, 2025). "Studies have shown increased CD34 expression in both severe and mild Graves’ orbitopathy (GO), with a significant correlation between CD34 expression and other inflammatory and fibrotic markers." (PMID 40853309, 2025).
trisomy (1 paper, 2016). A chromosomal abnormality consisting of the presence of one chromosome in addition to the normal diploid number. "Interestingly, in the case of MDS Patient 29 only 20% of the CD34+CD38−CLEC12A− CFCs were trisomy 8 positive, indicating a relatively large proportion of remaining normal HSCs in the BM of this particular patient." (PMID 27612176, 2016).
tumor syndrome (1 paper, 2013). "CD34+ CD38− phenotype was found in patients regardless of other epidemiological (age, sex), clinical (tumor syndrome) or biological (blood and/or medullar blasts) prognostic factors." (PMID 23667721, 2013).
Ureteral obstruction (1 paper, 2021). Obstruction of the flow of urine through the ureter. "In conclusion, the treatment with the small extracellular vesicles secreted by bone marrow mesenchymal stromal cells from trained rats carries pro-angiogenic miR-296 and delivers them into rats subjected to unilateral ureteral obstruction, possibly corroborating angiogenesis, via CD34 and HIF-1α." (PMID 34925478, 2021).
uterine tumor (1 paper, 2014). "The diagnosis of pulmonary metastases was obtained by reviewing the histology of the previous uterine tumor: the tumor cells were immunoreactive for CD10, PR, and smooth muscle actin (SMA), but negative for desmin, S100, CD34, CD 117, cytokeratins AE1AE3, CD68R, and ER." (PMID 24744931, 2014).
vascular malformation (1 paper, 2026). A non-neoplastic disorder that is the result of defects of vascular morphogenesis. "Positive staining for CD34, CD31, and D2‐40 indicated vascular endothelial origin; however, differentiation from vascular malformations remained essential." (PMID 41537446, 2026).
ventricular tachycardia (1 paper, 2015). A disorder characterized by an electrocardiographic finding of three or more consecutive complexes of ventricular origin with a rate greater than a certain threshold (100 or 120 beats per minute are commonly used). "Ventricular tachycardia inducibility did not increase in the animals that received CD34+ cells, and in fact decreased in the IV armed group (P = 0.08704), although not significantly." (PMID 25904069, 2015).
viral hepatitis (1 paper, 2018). An acute or chronic inflammation of the liver parenchyma caused by viruses. "Interestingly, there was a strong correlation between viral hepatitis load and circulating CD34+ cells in CHB patients and ETV treated groups (r2 = 0.8417, P < 0.001)." (PMID 29461203, 2018).
vitamin D deficiency (1 paper, 2015). A nutritional condition produced by a deficiency of VITAMIN D in the diet, insufficient production of vitamin D in the skin, inadequate absorption of vitamin D from the diet, or abnormal conversion of vitamin D to its bioactive metabolites. "RA patients with moderate disease activity presented with low vitamin D levels, low CD34+ cell count, increased PWV and cIMT; we found that vitamin D deficiency is associated to CD34+ cell reduction in peripheral blood, and with fibrinogen levels." (PMID 26241902, 2015). "In conclusion, our findings confirm Vitamin D deficiency in RA patients, and its association with inflammation; moreover, we suggest that CD34+ cell number is reduced in RA patients with moderate disease activity, mainly in subjects with lower vitamin D levels." (PMID 26241902, 2015).
vulvar carcinoma (1 paper, 2013). "The CD34 Chalkley counts for the vulvar carcinoma vascularity ranged from 3–14 (mean, 7.92; median, 8; SD, 2.29)." (PMID 24165149, 2013).
Wegener’s granulomatosis (1 paper, 2020). "Data on Granulomatosis with Polyangiitis (formerly Wegener’s granulomatosis) with CNS involvement is limited to a single case reported to the EBMT registry, which achieved a complete response following conditioning with Cy-ATG and CD34-selected aHSCT." (PMID 31558790, 2020).
X-linked hyper-IgM syndrome (1 paper, 2024). "Targeted gene editing to restore CD40L expression via homology-directed repair (HDR) in CD34+ hematopoietic stem and progenitor cells (HSPCs) represents a potential long-term therapy for X-linked hyper IgM syndrome." (PMID 40012884, 2024).
ZIKV infection (1 paper, 2023). "We determined if ZIKV infection of fetal CD34+ HSC affects their development in vivo into terminally differentiated immune cells." (PMID 36825016, 2023). "However, infection of fetal derived CD34+ HSC has more relevance to congenital and in utero ZIKV infection and the associated hematopathologies." (PMID 36825016, 2023). "However, since the potential effects of ZIKV infection on CD34+ HSC and their differentiation into terminal end-stage cells in vivo were not elucidated, we sought to evaluate this question." (PMID 36825016, 2023). "Our results show that these ZIKV neonatal humanized mice display discernible clinical signs of ZIKV infection and restricted development of CD34+ HSC into terminally differentiated B cells thus demonstrating the pathogenic effects of ZIKV on the developing hematopoietic system." (PMID 36825016, 2023).
tumor (2,136 papers, 1998 to 2026). "Although the myofibroblastic phenotype (α-SMA+/Vimentin+/CD34-) also increased overall with tumor grade and varied across acinar patterns, this association was comparatively weaker and less statistically robust than that observed for telocytes." (PMID 41683955, 2026). "CD34-MVD is an independent risk factor for postoperative tumor recurrence in patients with LUAD and can serve as a prognostic indicator for such patients." (PMID 39906069, 2025). "Immunofluorescence analysis showed that Kctd10 is co-localized with endothelial markers Cd31 and Cd34 in multiple subcutaneous tumors, suggesting that Kctd10 is associated with tumor angiogenesis." (PMID 40873559, 2025). "High CD34-MVD reduced the risk of tumor recurrence in a multivariate Cox proportional hazards regression model of postoperative tumor recurrence." (PMID 39906069, 2025). "Decreased intratumoral CD34 positive microvessels were associated with tumor development in patients with LUAD." (PMID 39906069, 2025). "CD34-MVD is an independent risk factor affecting postoperative tumor recurrence in patients with LUAD and can be used as a prognostic indicator for this group of patients." (PMID 39906069, 2025). "In solid tumours, CD34 expression is mainly associated with tumour angiogenesis, but its specificity as a CSC marker is low." (PMID 40665579, 2025). "CD34+ fibroblasts are intrinsic stromal components of nearly all organs, playing critical roles in matrix production, antigen presentation, and tumor-associated stromal remodeling." (PMID 39056788, 2024). "Regional expression of CD34 by tumor cells and by ramified neural cells in the associated cerebral cortex is an essential criterion for this entity." (PMID 39409964, 2024). "When comparing MVD measured by Nestin, and that measured by CD34, the first one showed more significant associations with larger tumor extent, and advanced tumor stage (P=0.001, 0.001 versus 0.006 and 0.009)." (PMID 39687450, 2024). "Compared with normal ECs, tumor-associated ECs display higher expression of the stem cell marker CD34 and the angiogenesis promoting markers CD61 (Integrin b3) and CD105 (Endoglin), and lower or absent expression of von Willebrand factor (vWF)." (PMID 38426109, 2024). "Mosquera and Fletcher suggested that the positive rate of CD34 is associated with tumor differentiation." (PMID 38903862, 2024). "Additional studies of larger cohorts with patient brain metastasis are necessary to evaluate the association between CD34 + and VM vessel density, tumor volume, edema, and other clinical variables." (PMID 38635031, 2024). "Human leukocytes in the tumor are most likely originated from the engrafted donor CD34+ cell, as several groups have demonstrated the loss of tumor-infiltrating immune cells in the process of PDX expansion in non-humanized mice." (PMID 37509357, 2023). "CD34 expression is mostly associated with tumor neovascularization or budding endothelial cells, whereas periodic acid Schiff (PAS)+ components represent polysaccharides as the intact basement in each tissue." (PMID 36781833, 2023). "In GBM, CD34-negative tumor cells were found within tube-like structures containing red blood cells associated with CD34-positive cells, indicating that the structure was continuous with normal blood vessels." (PMID 37568616, 2023). "In gastrointestinal stromal cancers (GISTs), the expression of CD34 (associated with tumor angiogenesis) varies depending on the location within the gastrointestinal tract where the GIST arises." (PMID 37894282, 2023). "In the first approach, tumor fragments were initially implanted into immune-deficient mice then engrafted into humanized mice that we established using cord blood CD34+ cells." (PMID 37509357, 2023). "On the other hand, the CD34 antigen is also expressed in the endothelium of tumor stromal blood vessels and is highly associated with tumor angiogenesis instead of its CAF expression." (PMID 37568639, 2023).
tumor (continued). "The density of CD34-positive lymphatic vessels varied among tumor types and was associated with lymph node metastasis and poorer prognosis." (PMID 38089632, 2023). "Studies have shown that CD34 expression in thyroid cancer is associated with more aggressive tumor behavior, including increased invasiveness, higher rates of metastasis, and poorer prognosis." (PMID 38089632, 2023). "High expression of CD68 was associated with CD34+ cells in tumor and low 5-year DFS in 45 patients with LSCC from China." (PMID 36686729, 2022). "The relationship of CD34 expression or BRAFV600E mutation in GNT with tumor survival (PFS or overall survival) have been studied, previously." (PMID 36307486, 2022). "The immunohistochemistry (IHC) method was applied to detect expressions of vascular endothelial growth factor (VEGF), hypoxia-inducible factor 1α (HIF-1α), and microvascular density-associated factor CD34 in tumor cells." (PMID 36046821, 2022). "Prominin 1 (PROM 1, or CD133) and VEGF receptor (VEGFR)-2 double-positive endothelial progenitor cells or CD34 positive cells were observed in the stroma, suggesting tumor-associated neoangiogenesis." (PMID 35311066, 2022). "The transplant of CD34+CD38− subpopulation into severe combined immuno-deficient (SCID) mice developed more tumor growth than CD34+CD38+ or CD34− subpopulations." (PMID 36230480, 2022). "The cells with CD34++ CD38− cell-surface antigen were only 0.2% in the tumor but had the potential to form neoplasms in the immune-deficient mice." (PMID 34359786, 2021). "Despite that higher MVD showed association with poor prognosis of tumor in general, CD34 MVD showed contradictory result to previous studies." (PMID 34642389, 2021). "Two main goals were pursued: Firstly, we aimed at the complete removal of residual tumor cells from the graft while minimizing CD34+/PBPCs loss from the PBPC product, thus simulating a clinical “purging” scenario." (PMID 34654486, 2021). "This concept is mainly based on the recruitment of CD34+ fibroblasts in tumour associated reactive stroma and on the possibility that perivascular CD34+ stromal cells are progenitors of myofibroblasts." (PMID 33916213, 2021). "We found that IL-1B regulates iNOS+ immune cell infiltration, without affecting either the accumulation of CD163+ immune cells or the growth of tumour-associated CD34+ blood vessels." (PMID 34290237, 2021). "Triple negative subtype and low CD34 MVD positivity in Notch 1 hotspots showed significant association with tumor recurrence." (PMID 34642389, 2021). "The expression of PSMA in tumor cells and associated neovascular endothelium were analyzed separately and the locations of vascular structures were confirmed by CD34 expression." (PMID 32703222, 2020). "In both instances (cord blood- or fetal liver-derived CD34 + cells), the major human leukocyte antigen (HLA) allele of the CD34 + cell donor must match the major HLA allele of the tumor cells." (PMID 32504051, 2020). "We found that MVD (anti-CD34) was associated with E and CI quantified in the complete tumor, and also with E, CI, and rBV quantified in the tumor periphery of SE micro-CT images." (PMID 33217988, 2020). "Although there was a significant association with tumor stage (P < 0.001), we focused on the impact of adjuvant therapies in the light of CD34‐positive CAFs and SMA‐positive CAFs in stromal tumor tissue." (PMID 31760702, 2020). "An increase in CD34+ tumor-associated blood vessel density was apparent in diaphragm specimens derived from mice injected with BACH1-overexpressing cells, as compared with control ES2 cells." (PMID 32132179, 2020). "We further assessed the expression of angiogenesis‐associated markers including CD31 and CD34 in LCM‐isolated cancer cells from tumor xenografts, and found both factors significantly upregulated when animals were subject to chemotherapy." (PMID 31493351, 2019).